AHR (aryl hydrocarbon receptor)
Diseases named in the same sentence as AHR in open-access papers (continued):
Sharing a sentence is not in itself a finding about the gene and the disease.
diabetes (continued). "This review explores the possible mechanistic crosstalk between AhR/CYP1 pathway activation and epigenetic alterations in the context of diabetes development." (PMID 40408591, 2025). "Thus, AhR may be a key factor in the development of diabetes." (PMID 39944639, 2025). "The levels of AHR and IRF4 expression were analyzed in both the healthy controls and patients with type 1 diabetes mellitus." (PMID 39211721, 2024). "The present review aims at providing significant insight into the physiological and pathological role of AhR and its regulated enzymes, such as cytochrome P450 1A1 (CYP1A1) and CYP1B1 in both types of diabetes." (PMID 36418969, 2022). "We determined that diabetes-mediated leukostasis, oxidative stress, and inflammation in the retina of STZ-diabetic mice were all significantly lower when treated with the AhR agonist VAF347." (PMID 33919327, 2021). "To ensure relevance of this experimental group for effect on diabetes, we used NOD AhR knockout mice at 12 weeks of age when approximately 60% of islets are infiltrated, but prior to clinical manifestations." (PMID 33552063, 2020). "In endothelial cells, high glucose activates AhR, which leads to activation of the TSP-1 gene, a potent antiangiogenic and proatherogenic protein involved in the development of vascular complications in diabetes." (PMID 41440753, 2025). "It has been reported that serum AhR levels are inversely correlated with β-cell function in patients without known diabetes mellitus." (PMID 40508196, 2025). "This could possibly be because AhR in CD4+ T cells may have increased the frequency of Treg cells, suppressing the development of diabetes." (PMID 36418969, 2022). "Accordingly, we propose that the AhR agonist VAF347 would be a good therapeutic candidate for diabetes and its complications, especially non-proliferative diabetic retinopathy." (PMID 33919327, 2021). "This means that as the body burden of TCDD declined to levels that could not activate AhR, Cyp1a1 gene expression within the liver diminished, leading to diabetes initiation within these mice." (PMID 36418969, 2022). "To determine if the AhR agonist VAF347 treatment is sufficient to halt capillary degeneration in the diabetic retina, we isolated the capillary beds of retinas (n = 5) from non-diabetic, VAF347-treated STZ-diabetic, and untreated STZ-diabetic C57BL/6 mice, eight months after diabetes was confirmed." (PMID 33919327, 2021). "In the non-obese diabetic (NOD) mouse model of type 1 diabetes mellitus (T1DM) development, TCDD activated AHR, increasing Foxp3+ T cells that exert anti-inflammatory effects against effector T cells, preventing T1DM development." (PMID 38612627, 2024). "The involvement of AHR/CYP1A1 activation is suggested in the development of non-alcoholic fatty liver disease (NAFLD) and the consequent onset of diabetes." (PMID 38731818, 2024). "Sera were evaluated in both untreated (C57BL/6) and AhR agonist VAF347-treated (+VAF347) non-diabetic (ND) and STZ-diabetic (DB) mice to quantify average blood glucose levels through a glycated hemoglobin A1c (HbA1c) analysis at week 6 and 29 after diabetes was confirmed." (PMID 33919327, 2021).
prostate carcinoma (48 papers, 2010 to 2025). A carcinoma that arises from epithelial cells of the prostate gland. "Some studies have demonstrated the association of AhR activity levels with prostate cancer aggressiveness, supporting its use as a prognostic biomarker." (PMID 39184676, 2024). "In our current study, 22q-SE influenced prostate cancer susceptibility by altering the binding affinity of AhR and regulating the FAM227A expression." (PMID 38410974, 2024). "AhR's activity levels have been associated with the aggressiveness of prostate cancer, suggesting its potential as a prognostic biomarker." (PMID 39184676, 2024). "In conclusion, our findings provide some evidence that rs6001092 in 22q-SE contributes to prostate cancer risk and development mediated by AhR and the upregulated FAM227A expression." (PMID 38410974, 2024). "In prostate cancer, AHR has been implicated in regulating AR signaling, a key driver of tumor growth and progression." (PMID 39600743, 2024). "Among these, the Aryl Hydrocarbon Receptor (AHR), a ligand-activated transcription factor initially associated with detoxifying environmental pollutants, has emerged as a critical player in prostate cancer biology." (PMID 39600743, 2024). "Strong nuclear AHR expression is observed in the invasive phenotype, and an elevated nuclear AHR expression is associated with poor prognosis in human prostate cancer." (PMID 30972102, 2019). "Certain AHR variants alter its ability to bind ligands or regulate downstream signaling pathways, contributing to differences in how AA men respond to environmental carcinogens and how their prostate cancer progresses." (PMID 39600743, 2024). "AHR expression is upregulated in androgen-independent prostate cancer cells, indicating its role in maintaining hormone-independent proliferation, a characteristic associated with more aggressive and treatment-resistant forms of prostate cancer." (PMID 39600743, 2024). "Here, increased expression of AhR was observed in Kyn treated prostatic cancer cells, suggesting that AhR might be involved in the Kyn associated chemoresistance." (PMID 34657603, 2021). "AhR activation by TCDD may increase prostate cancer risk, particularly in humans and animal models susceptible to prostate carcinogenesis." (PMID 26154658, 2015). "Similarly, TDO2-induced generation of Kyn can be associated with prostate cancer by acting on AhR." (PMID 41282989, 2025). "The current study highlights that AhR acts as an environmental sensor of BaP and is involved in the SE-mediated prostate cancer risk, which may provide new insights into the etiology of prostate cancer associated with the inherited SE variants under environmental carcinogen stressors." (PMID 38410974, 2024). "Specifically, we demonstrated that TDO2 increased the survival of dormant prostate cancer cells through a TDO2-Kyn-AhR signalling axis, which in turn promoted tumour dormancy." (PMID 40759641, 2025). "In this study, we demonstrated that the tryptophan catabolism pathway TDO2-Kyn-AhR maintains the survival of ADT-induced dormant prostate cancer cells and promotes the recurrence and aggressive growth of CRPC cells." (PMID 40759641, 2025). "Specifically, activation of the AhR/c-Myc pathway is considered to confer resistance to chemotherapy in prostate cancer." (PMID 39852970, 2025). "In prostate cancer, the tumor modulatory effects of AhR appear to be context-dependent, differing based on androgen sensitivity or refractoriness." (PMID 38807762, 2024). "Natural AhR agonists, such as indoles found in cruciferous vegetables, have been shown to effectively reduce prostate cancer cell viability and induce apoptosis by altering gene expression involved in cell cycle regulation and apoptosis." (PMID 39184676, 2024). "This study highlighted the dual role of AhR in prostate cancer progression, suggesting that the specific molecular and cellular environment impacts AhR's effect on tumor progression." (PMID 39184676, 2024).
prostate carcinoma (continued). "Elevated AHR expression has been observed in androgen-independent prostate cancer cells, linking AHR to the transition to CRPC, a highly aggressive and treatment-resistant form of the disease." (PMID 39600743, 2024). "In the context of prostate cancer, AhR plays a complex role, capable of both promoting and inhibiting tumor growth depending on the cellular environment and the presence of specific coactivators and corepressors." (PMID 39184676, 2024). "In conclusion, while socioeconomic and environmental factors undoubtedly contribute to the disparities observed in prostate cancer outcomes, there is mounting evidence that intrinsic biological differences, particularly in AHR signaling, play a critical role." (PMID 39600743, 2024). "Ethnic differences in AHR signaling have been identified as one of the potential contributors to disparities in prostate cancer outcomes." (PMID 39600743, 2024). "This review highlights the critical roles of the AHR and AR signaling pathways in the aggressive nature of prostate cancer within AA populations." (PMID 39600743, 2024). "The table highlights the key coactivators and corepressors involved in AhR’s dual functionality in prostate cancer, demonstrating their roles in either promoting or suppressing tumor activity." (PMID 39184676, 2024). "For instance, in vitro studies using prostate cancer cell lines have demonstrated that activation of AhR with ligands such as dioxins and certain polycyclic aromatic hydrocarbons leads to increased AR transcriptional activity and tumor cell proliferation." (PMID 39184676, 2024). "Genetic studies have identified certain AHR variants that are more prevalent in AA populations, suggesting a potential genetic basis for the differences in AHR activity and its impact on prostate cancer development." (PMID 39600743, 2024). "It has been reported that AHR activation in gastric and prostate cancer cells induces MMP-9 upregulation." (PMID 39125717, 2024). "For instance, AhR activation has been linked to the upregulation of RAB3D, which promotes prostate cancer progression through the PI3K/AKT pathway." (PMID 39184676, 2024). "This review aims to synthesize current research on the role of AhR in prostate cancer, exploring its potential as a therapeutic target and biomarker." (PMID 39184676, 2024). "While the potential of AhR as a therapeutic target in prostate cancer is promising, several challenges remain." (PMID 39184676, 2024). "Some studies emphasized the necessity for more detailed mechanistic studies to fully understand AhR's role in prostate cancer." (PMID 39184676, 2024). "This degradation mechanism, mediated by AhR, resulted in the suppression of prostate cancer cell proliferation, with pronounced effects on hormone-refractory prostate cancer cell lines." (PMID 39184676, 2024). "Targeting both AHR and AR signaling is a promising strategy to address the ethnic disparities in prostate cancer outcomes." (PMID 39600743, 2024). "AHR’s role in immune regulation adds another layer of complexity to its impact on prostate cancer outcomes." (PMID 39600743, 2024). "In this study, we examined urolithin A’s ability to enhance the cytotoxicity of PBMCs from prostate cancer patients against cancer cells and assessed the role of AhR in this effect." (PMID 39850551, 2024). "Preclinical studies have demonstrated that AHR antagonists and modulators can effectively inhibit the pro-tumorigenic effects of AHR signaling in cancer models, including prostate cancer." (PMID 39600743, 2024). "The AhR plays a multifaceted role in the progression of prostate cancer, demonstrating both tumor-promoting and tumor-suppressing activities." (PMID 39184676, 2024). "By gaining a deeper understanding of the roles of AHR and AR signaling in prostate cancer, particularly in the context of ethnic diversity, we aim to work toward reducing these disparities and improving outcomes for all patients." (PMID 39600743, 2024).
prostate carcinoma (continued). "In vitro experiments with AhR agonists in androgen-sensitive human prostate cancer cells have corroborated these murine studies." (PMID 38807762, 2024). "Previous studies showed that BaP affected the JAK2/STAT3 pathway by activating AhR to promote prostate cancer progression." (PMID 38410974, 2024). "This narrative review synthesizes current research on AhR’s multifaceted roles in prostate cancer, evaluates its potential as a biomarker, and discusses the therapeutic implications of targeting AhR, particularly for hormone-refractory prostate cancer." (PMID 39184676, 2024). "AhR is highly expressed and constitutively active in androgen-independent (hormone-refractory) prostate cancer cells relative to androgen-sensitive prostate cancer cells." (PMID 38807762, 2024). "In contrast, the agonist of AhR hasn’t shown such influence on the NK activity of PBMCs from patients with prostate cancer." (PMID 39850551, 2024). "This dual role of AhR is highlighted in studies where its overexpression enhances Src kinase activity, thereby promoting AR signaling and prostate cancer progression." (PMID 39184676, 2024). "AHR’s role in prostate cancer is complex, particularly when considering its interaction with AR signaling." (PMID 39600743, 2024). "Tabulated form of various AhR modulators and their mechanisms involved in reducing prostate cancer cell viability and inducing apoptosis." (PMID 39184676, 2024). "Emerging research has highlighted the aryl hydrocarbon receptor (AhR) as a potential target in the fight against prostate cancer." (PMID 39184676, 2024). "This research emphasized AhR's role as a coactivator of AR, highlighting its potential in promoting prostate cancer progression." (PMID 39184676, 2024). "A study illustrated that AhR overexpression enhances Src kinase activity, which in turn promotes AR signaling and prostate cancer progression." (PMID 39184676, 2024). "Given the complexity of AhR's role in prostate cancer, further research is necessary to fully elucidate its mechanisms and develop effective AhR-targeted therapies." (PMID 39184676, 2024). "AHR, traditionally recognized for its role in detoxifying environmental carcinogens, has recently been identified as playing a key role in prostate cancer progression." (PMID 39600743, 2024). "In prostate cancer, AhR interacts with AR signaling in a context-dependent manner, exhibiting both enhancement and inhibition of AR activity." (PMID 39184676, 2024). "A study utilized immunohistochemical analysis to assess AhR levels in prostate cancer tissue samples." (PMID 39184676, 2024). "This review investigates the emerging significance of the aryl hydrocarbon receptor (AhR) in prostate cancer, focusing on its role in modulating androgen receptor (AR) signaling and its potential as a therapeutic target." (PMID 39184676, 2024). "Central to this investigation are the AHR and AR signaling pathways, which play crucial roles in the progression and severity of prostate cancer." (PMID 39600743, 2024). "AhR also plays a significant role in modulating the immune system within the tumor microenvironment, influencing prostate cancer progression." (PMID 39184676, 2024). "Studies have consistently shown that AA men exhibit higher levels of AHR expression in prostate cancer tissues compared to Caucasian men, leading to more aggressive tumor phenotypes and higher mortality rates." (PMID 39600743, 2024). "The overexpression of AhR was shown to enhance Src kinase activity, further promoting AR signaling and prostate cancer progression." (PMID 39184676, 2024). "In androgen-refractory prostate cancer models, however, AhR has been suggested to act as a tumor promoter." (PMID 38807762, 2024). "Synthetic AhR agonists have also demonstrated significant preclinical efficacy in reducing tumor growth by selectively activating AhR in prostate cancer cells, thereby minimizing off-target effects." (PMID 39184676, 2024).
prostate carcinoma (continued). "The review summarized the preclinical efficacy of various AhR modulators, showing promising results in reducing prostate cancer cell viability and inducing apoptosis." (PMID 39184676, 2024). "The complexity of AhR's role in prostate cancer underscores the necessity for context-dependent therapeutic strategies targeting AhR." (PMID 39184676, 2024). "Further studies are needed to understand the crosstalk of the AhR and AR pathways and how they impact prostate cancer progression in both androgen-sensitive and androgen-refractory settings." (PMID 38807762, 2024). "Immunohistochemistry of human prostate cancer tissues shows increasing AhR expression with tumor grade." (PMID 38807762, 2024). "As an alternative approach for controlling PARP7 in prostate cancer cells, we turned to the transcription factor AHR, a member of the basic helix-loop-helix /Per-AHR nuclear translocator-Sim protein family." (PMID 37077937, 2023). "The possibility that additional factors regulated through AHR contribute to the RBN2397 vulnerability in prostate cancer cells cannot be excluded." (PMID 37077937, 2023). "Taken together, the data show that RBN2397 can be used to inhibit growth in prostate cancer cells where PARP7 is induced by AHR signaling." (PMID 37077937, 2023). "PARP7 expression levels can be regulated in prostate cancer cells using ligands for AR and AHR, including the NEPC line NCI-H660." (PMID 37077937, 2023). "RBN2397 inhibits the growth of prostate cancer cells in culture when cells are treated with ligands that activate the AR, or the aryl hydrocarbon receptor, and induce PARP7 expression." (PMID 37077937, 2023). "An alternative explanation, at least in prostate cancer cells, is that gene expression induced by AR and AHR creates a PARP7 dependency for cell growth." (PMID 37077937, 2023). "In reporter gene assays using prostate cancer cells, significant correlations between antiandrogenic and AhR agonistic activities have been demonstrated by several PAHs at 100 nM." (PMID 36612408, 2022). "The main goal of this study was to demonstrate if AhR activation by certain indoles can result in the degradation or at least suppression of AR activity in prostate cancer cells." (PMID 36613955, 2022). "We have shown that carbidopa as an AhR agonist attenuates pancreatic cancer growth while other investigators have shown that carbidopa suppresses prostate cancer growth via AhR-mediated ubiquitination and degradation of androgen receptor." (PMID 35997090, 2022). "More than a decade ago, a different prostate cancer therapeutic strategy was suggested, assuming suppression of AR function through activation of the aryl hydrocarbon receptor (AhR), i.e., an indirect approach." (PMID 36613955, 2022). "AHR has been shown as a β-catenin target gene in prostate cancer cells so that increased β-catenin activity leads to increased AHR expression." (PMID 34198826, 2021). "The observation that AhR inhibition increased the apoptosis rate of LNCaP and VCaP cells in vitro provided evidence that AhR inhibition represents a novel strategy for targeted therapy for prostatic cancer treatment." (PMID 34657603, 2021). "More importantly, enhanced expression of AhR was found in tumor tissues from C-R patients with prostatic cancer, indicating that Kyn promoted AhR activation to mediate drugs resistance in prostatic cancer." (PMID 34657603, 2021). "On the other hand upregulation of AhR, for example, in the esophageal squamous cell carcinoma cell lines, prostate cancer or pancreatic cancer reveals suppressive effect toward cancer." (PMID 32899152, 2020). "Taken together, our study implicates Carbidopa for the first time in effective suppression of prostate cancer via a mechanism, involving AHR-mediated proteasomal degradation of AR." (PMID 32404918, 2020). "TCDD and B[a]P also up-regulate MMP-9 in prostate cancer cells, while AHR knockdown decreases invasion of prostate cancer cells in matrigel." (PMID 33396563, 2020).